OR52J3 (olfactory receptor family 52 subfamily J member 3)
Description:
Odorant receptor.
Synonyms: OR11-32
Tractability: Antibody: UniProt places it where antibodies can reach, with medium confidence; UniProt predicts a signal peptide or a membrane-spanning region; its Gene Ontology location is reachable by antibodies, with medium confidence.
Gene: Protein-coding gene on chromosome 11 (5,046,526 to 5,047,461, forward strand). Ensembl gene ENSG00000205495.
Subcellular location: Cell membrane
Pathways (Reactome):
Sensory Perception: Expression and translocation of olfactory receptors
Gene Ontology:
Molecular function: olfactory receptor activity; G protein-coupled receptor activity
Biological process: detection of chemical stimulus involved in sensory perception of smell; G protein-coupled receptor signaling pathway; nervous system process
Cellular component: plasma membrane; membrane
Genetic constraint (gnomAD): Missense variants: 445 observed, 406.13 expected, observed/expected ratio (o/e) 1.1, 90% interval 1.01 to 1.18. Synonymous variants: 155 observed, 147.69 expected, observed/expected ratio (o/e) 1.05, 90% interval 0.92 to 1.2.
Homologues: Orthologues: chimpanzee OR52J3 (99% identical), dog OR52J3 (90% identical), rabbit OR52J3 (83% identical), mouse Or52j3 (82% identical), rat Or52j3b (81% identical), rat Or52j3 (81% identical), tropical clawed frog or52m1 (46% identical). Paralogues in human: OR52E8 (59% identical), OR52E4 (58% identical), OR52E6 (57% identical), OR52E2 (56% identical), OR52E5 (56% identical), OR52D1 (55% identical), OR52B2 (52% identical), OR52R1 (52% identical), OR52K1 (51% identical), OR52H1 (51% identical), OR52K2 (51% identical), OR52A5 (50% identical), and 39 more.